VCAM1 (vascular cell adhesion molecule 1)
Diseases named in the same sentence as VCAM1 in open-access papers (continued):
Sharing a sentence is not in itself a finding about the gene and the disease.
atherosclerosis (continued). "Although VCAM-1 has been well documented to be associated with the development of atherosclerosis, several studies also demonstrated that the expression of VCAM-1 was increased in patients with hypertension." (PMID 22778962, 2012). "Diabetic ApoE/glutathione peroxidase-1 double KO mice show enhanced atherosclerosis compared to diabetic mice deficient in ApoE alone associated with enhanced VCAM-1 expression and macrophage recruitment." (PMID 22489274, 2012). "In the present study, we used the genetically modified apolipoprotein E deficient (ApoE−/−) mouse, a widely used mouse model of atherosclerosis and natural hypercholesterolemia, to study the effect of dyslipidemia on endothelial VCAM-1 expression." (PMID 20856927, 2010). "After OSE, we also observed strong expression of VCAM-1, a molecule that recruits immune cells and is implicated in the generation of atherosclerosis." (PMID 19575822, 2009). "Decreased atherosclerosis correlated with a strong down-regulation in the expression of adhesion molecules, such as VCAM-1 and ICAM-1, by p55 TNFR deficient endothelium." (PMID 19582157, 2009). "The overall association scores of CHI3L1 in coronary artery disease, peripheral arterial disease, carotid atherosclerosis, and atherosclerosis were 0.102, 0.091, 0.064, and 0.062, respectively, which are similar to the overall association scores of VCAM1 and ITGAX." (PMID 38177294, 2024). "Additionally, the upregulation of vascular cell adhesion molecule-1 by CRH has been shown to promote atherosclerosis progression in LDL receptor-deficient mice." (PMID 39742022, 2024). "In advanced atherosclerosis, Vcam1 mRNA, encoding vascular cell adhesion molecule 1, was increased in the common carotids and Cd68, a highly expressed mRNA in macrophages, was increased in the carotid bifurcation, indicating that these sites were in different phases of atheroprogression." (PMID 38270847, 2024). "The determination of cut-off values for adhesion molecules, particularly VCAM-1, has already been proven beneficial for the detection of pathologies associated with atherosclerosis, such as peripheral arterial disease, atrial fibrillation, post-acute myocardial infarction, and heart failure." (PMID 38255155, 2023). "ICAM-1 and VCAM-1 have been associated with atherosclerosis and CVD risk even in HIV(-) population." (PMID 36930649, 2023). "Consistently, TRAF5-deficient mice present with increased atherosclerosis, an effect likely caused by enhanced VCAM-1-dependent leukocyte migration and enhanced expression of MCP-1 and C-X-C motif ligand 1 (CXCL1), resulting in accelerated leukocyte recruitment into atherosclerotic lesions." (PMID 35252400, 2022). "Similarly, Icam1 has also been implicated in tumor metastasis in the lung, and both Icam1 and Vcam1 contribute to atherosclerosis, which are diseases associated with cigarette smoking." (PMID 36613693, 2022). "In addition, the occurrence of atherosclerosis was positively associated with serum MMP8 concentration that increased the expression of vascular cell adhesion molecule-1 (VCAM-1)." (PMID 35145983, 2022). "On the other hand, aortic VCAM1 expression has been long correlated with the severity of the atherosclerotic disease and cardiovascular risk factors; therefore, it plays a role in the pathogenesis of atherosclerosis." (PMID 36555552, 2022).
atherosclerosis (continued). "Subclinical atherosclerosis plaque occurrence in SSc patients was reported to be associated with smoking, higher blood pressure, impaired kidney function, high levels of IL-6, serum levels of vascular cell adhesion molecule 1 and with ACA." (PMID 35769143, 2022). "Furthermore, ICAM‐1 and VCAM‐1 are involved in the all stage of atherosclerosis, an important risk factor in pathology of AIS." (PMID 35353946, 2022). "While VCAM1 was not downregulated by treatment with the CM from GW3965‐treated EOCs in culture, administration of the CM to atherosclerosis‐prone mice did show a downregulation of endothelial VCAM1 in the aortic sinus, which was associated with a decrease in plaque area." (PMID 33231376, 2021). "The expression of VCAM-1 is known to be closely associated with the atherosclerosis process." (PMID 33839697, 2021). "Indeed, in atherosclerosis prone, VCAM1-deficient mice (ApoE−/−;VCAM1D4D/D4D), fatty streak formation and atherogenesis is blunted when compared to atherosclerosis-prone mice that do express VCAM1 (ApoE−/−VCAM1+/+ mice)." (PMID 33562658, 2021). "The activation of the AGE-RAGE signaling pathway can induce the production of NF-κB, VCAM-1, tissue factor, and inflammatory factors and is one of the most relevant signaling pathways associated with chronic diseases such as diabetes, atherosclerosis, and cancer." (PMID 34746316, 2021). "After 16 weeks, they found that the ApoE−/−Ppia−/− mice developed significantly reduced atherosclerosis compared with ApoE−/− mice, and CyPA deficiency was associated with decreased vascular cell adhesion molecule 1 (VCAM-1) expression, ROS, inflammation, ECs activation and apoptosis." (PMID 31825469, 2019). "Taken together, these data suggest that KRIT1+/− mice have a significantly increased susceptibility to fatty streaks deposition and VCAM-1 mRNA expression in atherosclerosis-prone regions of the aorta under stressful conditions, such as a chronic consumption of HF diets." (PMID 31590384, 2019). "YAP located in the nucleus under DF promotes endothelial cell ICAM1 and VCAM1 expression for monocyte adherence, which is correlated with key pathogenic events in atherosclerosis such as endothelial thickening and the recruitment of monocytes, which eventually turn into plaques." (PMID 31730006, 2019). "Atherosclerosis caused by oxidative damage, and evidenced by increased circulating mononuclear superoxide production and vascular cell adhesion molecule-1 (VCAM-1) and triggered by NADPH oxidase (NOx) and NF-kB activation in CKD patients, is associated with IV iron administration." (PMID 30347874, 2018). "Serum homocysteine and VCAM1 are considered risk factors for vascular disease and atherosclerosis." (PMID 28985743, 2017). "ICAM-1 and VCAM-1 modify the process underlying the adhesion between endothelial cells and monocytes, which leads mononuclear cells into artery intima and results in the early lesions of atherosclerosis." (PMID 25933220, 2015). "Using animal models, Cybulsky and Gimbrone demonstrated that LDL could promote the expression of VCAM-1 in endothelial cells and that hypercholesterolemia could cause atherosclerosis-related pathophysiological changes in the arteries." (PMID 26622332, 2015). "VCAM-1 is expressed on the impaired endothelium is regulated by various factors such as oxidative stress and cytokines and has been considered to be an important risk factor to the progression of atherosclerosis and cardiovascular events." (PMID 22675380, 2012).
atherosclerosis (continued). "To determine whether sVCAM-1 or insoluble (cell-associated) VCAM-1 mediates α9β1-dependent early atherosclerosis in vivo, we examined the co-localization of VCAM-1 with Mac-3, a marker for mature macrophages, in atherosclerotic plaques from α9Mye-KOApoe−/− and control α9WTApoe−/− mice." (PMID 39036986, 2024). "Moreover, VCAM-1 may be associated with the severity of atherosclerosis and the prediction of cardiovascular disease." (PMID 36835296, 2023). "Because VCAM-1 is an essential adhesion molecule involved in atherosclerosis initiation and progress, the drastic difference in its expression in adult arteries and veins suggest that it may correlate with the low susceptibility of atherosclerosis in veins." (PMID 26537113, 2015). "The two genes encode cell adhesion molecules (CAMs), namely ICAM-1 and VCAM-1, that are expressed on the surface of activated endothelial cells in response to inflammatory stimuli and mediate the attachment of circulating leukocytes to the endothelium, an early step of atherosclerosis." (PMID 25575156, 2015). "In addition, VCAM-1 has been linked with the pathogenesis of atherosclerosis." (PMID 26622332, 2015). "Previous studies have demonstrated that a remarkable reduction in atherosclerosis in CyPA-deficient mice might be caused by decreased vascular cell adhesion molecule 1 (VCAM-1) expression, which is highly expressed in activated ECs and promoted atherosclerosis." (PMID 24520398, 2014). "This resulted in lower expression of NF-κB target genes encoding adhesion molecules (VCAM-1, ICAM-1, E-selectin) and chemokines (CX3CL1, MCP-1, RANTES)––molecules that orchestrate endothelial inflammation and leukocyte recruitment in atherosclerosis." (PMID 40871686, 2025). "VCAM-1 is considered a promising target for non-invasive imaging of atherosclerosis since it is expressed by endothelial cells early in the atherosclerotic process and can therefore be targeted to change the course of disease." (PMID 40941627, 2025). "Since VCAM-1 on endothelial cells plays a major role in initiating and driving atherosclerosis development, it is likely that this increased VCAM-1 expression in coronary arteries at least in part explains the increased coronary artery atherosclerosis." (PMID 40403091, 2025). "Elevated ICAM1 and VCAM1 levels are considered hallmarks of a pro-inflammatory endothelium and contribute to vascular remodeling and atherosclerosis." (PMID 41293173, 2025). "Lp(a) also induces endothelial dysfunction by upregulating adhesion molecules like VCAM-1 and E-selectin, promoting atherosclerosis." (PMID 40095552, 2025). "Considering the novelty of selectively targeting domain 2 or 3 of VCAM-1 as a strategy for directly combating monocyte recruitment, the tested mAbs represent an intriguing platform for site-specific atherosclerosis nanotherapeutics." (PMID 41367412, 2025). "Onex was engineered with the VHPK peptide, to construct V-Onex, specifically targeting vascular cell adhesion molecule-1 (VCAM-1), which is strongly upregulated in inflamed endothelial cells during atherosclerosis." (PMID 41009453, 2025). "VCAM-1 plays a significant role in maintaining homeostasis and is involved in various pathological conditions, including cancer, atherosclerosis, atrial fibrillation, myocardial infarction, stroke, asthma, obesity, and kidney diseases." (PMID 39859506, 2025). "Atherosclerosis was reduced in remdesivir-treated mice along with decreased VCAM-1 expression in aortic roots of ApoE −/− mice, which indicates potential anti-inflammatory effects of remdesivir." (PMID 40598260, 2025). "NF-κB promotes the expression of a series of proinflammatory cytokines and various atherosclerosis-related genes, such as VCAM-1, VEGF, and RAGE." (PMID 41257262, 2025).
atherosclerosis (continued). "OxLDL is a key player in atherosclerosis, as it is highly immunogenic and stimulates endothelial cells to express adhesion molecules like vascular cell adhesion molecule-1 (VCAM-1), facilitating the adhesion and transmigration of monocytes into the intima." (PMID 40138141, 2025). "In conclusion, this study demonstrates the therapeutic potential of a novel panel of anti-VCAM-1 mAbs for treating atherosclerosis by employing a series of in vitro models mimicking vascular inflammation." (PMID 41367412, 2025). "Although the pro-inflammatory function of VCAM-1 in the pathogenesis of atherosclerosis and acute coronary syndromes is well-documented, efforts to translate this knowledge into targeted therapies have only recently developed." (PMID 40599142, 2025). "Notch3 expression was largely confined to fcVSMCs in both atherosclerosis and injury, whereas Vcam1 was highly expressed by imVSMCs and down-regulated in fcVSMCs." (PMID 40577585, 2025). "Targeting VCAM-1 for the development of non-invasive imaging techniques to identify atherosclerosis early in the process has been and continues to be a long-standing goal." (PMID 40941627, 2025). "VCAM-1 involvement in pathological cell recruitment has been defined across a range of inflammatory disease pathologies, including atherosclerosis, asthma, rheumatoid arthritis, and colitis." (PMID 40095109, 2025). "The therapeutic potential of anti-VCAM-1 antibodies has been investigated in various experimental inflammatory disease models, including atherosclerosis, asthma, and rheumatoid arthritis." (PMID 40095109, 2025). "While the pro-inflammatory function of VCAM-1 in the development of atherosclerosis is well documented, efforts to translate this understanding into targeted therapies have only recently accelerated." (PMID 40599142, 2025). "SCFAs act on endothelial cells to prevent vascular cell adhesion molecule-1 (VCAM-1) and IL-6 and IL-8 pro-inflammatory expression, reducing inflammation and cell adhesion to prevent atherosclerosis." (PMID 40051430, 2025). "Soluble Vascular Cell Adhesion Molecule-1 (sVCAM-1) seems to exhibit higher specificity in identifying atherosclerosis when compared to other markers." (PMID 39859506, 2025). "It mitigates vascular inflammation associated with atherosclerosis by downregulating the expression of intracellular adhesion molecule-1 (ICAM-1) and vascular cell adhesion molecule-1 (VCAM-1)." (PMID 40852589, 2025). "VCAM-1 is a prominent membrane protein that mediates the attachment of leukocytes to ECs and consequently plays a key role in the development of atherosclerosis." (PMID 40943070, 2025). "The present study also demonstrated that cell-associated VCAM-1, rather than sVCAM-1, plays a crucial role in mediating α9β1-dependent early atherosclerosis, as evidenced by reduced VCAM-1/Mac-3 co-localization in α9Mye-KOApoe−/− plaques." (PMID 39036986, 2024). "Accordingly, because the study was retrospective, we cannot measure the more specific markers for understanding immune function and atherosclerosis development, like VCAM-1 or CD93." (PMID 39797206, 2024). "Very recently, atherosclerosis has emerged as a new considerable ICIs-mediated side effect in cancer patients through VCAM-1 and ICAM-1 overexpression in the luminal membrane of vascular endotheliocytes." (PMID 39457081, 2024). "VCAM-1 is one of the crucial molecules that contribute to the formation of atherosclerosis, becoming activated on the surface of arterial endothelial cells." (PMID 39337364, 2024). "In the context of atherosclerosis, it is known that VCAM‐1 promotes monocyte adhesion and activation into macrophages, thereby contributing to lesion progression." (PMID 39639552, 2024). "Another study found that VCAM-1 expression is increased in atherosclerotic lesions, suggesting its critical role in atherosclerosis initiation." (PMID 39830114, 2024).
atherosclerosis (continued). "The resulting decrease in the expression of the NF-κB target gene VCAM-1 is expected to curtail the initiation and progression of atherosclerosis." (PMID 38335214, 2024). "During this process, the AIM2 inflammasome in macrophages not only contributed to the induction of vascular cell adhesion protein-1 (VCAM-1) expression in atherosclerosis, but also limited cholesterol transport and facilitated foam cell formation." (PMID 39600708, 2024). "Previous studies have found that HDAC1/2 promotes arterial endothelial cell surface vascular cell adhesion molecule-1 expression and atherosclerosis through inhibition of STAT3 acetylation-dependent GATA6 promoter methylation." (PMID 38444939, 2024). "They examined cellular adhesion molecules, soluble ICAM-1 and soluble-VCAM-1, which are biological markers that show the progression and consequences of endothelial inflammation and atherosclerosis." (PMID 38233818, 2024). "The relative upregulation of inflammatory processes in the transcriptomics data can most likely be attributed to genes encoding pro-inflammatory proteins such as VCAM1, ICAM1, and SELE, which are shown to be elevated in the initial stages of atherosclerosis." (PMID 39695567, 2024). "VCAM-1 also plays a key role in leukocyte–endothelial cell signal translation and in the development of atherosclerosis." (PMID 38672153, 2024). "VCAM-1 has also been identified as the primary adhesion molecule in individuals with atherosclerosis, and is detectable on the surface of endothelial cells in the early stages of atherosclerosis development." (PMID 39830114, 2024). "It significantly increases the expression of intercellular adhesion molecule 1 (ICAM-1) and vascular cell adhesion molecule 1 (VCAM-1), thereby accelerating the inflammatory response of atherosclerosis." (PMID 38791032, 2024). "Even in atherosclerosis, the contribution of VCAM-1 to monocyte accumulation in the early stages of disease progression has been reported." (PMID 38339104, 2024). "Accordingly, endothelial deletion of ALK5 or TGFBR2 in the ApoE−/− atherosclerosis mouse model reduces atherosclerosis plaque burden, plaque collagen content, fibronectin deposition and VCAM-1 expression." (PMID 38323651, 2024). "Elevated levels of ICAM-1 and VCAM-1 contribute to the initiation and progression of atherosclerosis by promoting the infiltration of inflammatory cells into the vascular wall, thereby exacerbating the inflammatory response and plaque formation." (PMID 38915995, 2024). "These inflammatory cytokines are responsible for inducing the expression of adhesion molecules such as vascular cell adhesion molecule-1, which leads to atherosclerosis and subsequently promotes calcification progression." (PMID 39234605, 2024). "For example, during atherosclerosis, endothelial cells express VCAM-1, and this assists in the migration of monocytes to the atherosclerotic plaque." (PMID 39769411, 2024). "Anti-VCAM-1 antibodies have been tested in mouse models for their effectiveness against asthma and atherosclerosis." (PMID 39769411, 2024). "Vascular cell adhesion protein 1 (VCAM-1) is a cell adhesion molecule implicated in a range of diseases, including atherosclerosis, immunological disorders (e.g., rheumatoid arthritis (RA) and asthma), and cancer, among others." (PMID 39769411, 2024). "Although the role of VCAM-1 in the cardiovascular system is not fully understood, several studies have shown that VCAM-1 is expressed in various CVDs such as atherosclerosis, CAD, stroke, MI, CHF, and arterial hypertension." (PMID 39596487, 2024). "This modulation enhances the expression of intercellular adhesion molecule-1 (ICAM-1), MCP-1, vascular cell adhesion molecule 1 (VCAM-1), and IL-6, potentially accelerating the progression of atherosclerosis." (PMID 39726601, 2024).